OLFML3 (olfactomedin like 3)
Description:
Secreted scaffold protein that plays an essential role in dorsoventral patterning during early development. Stabilizes axial formation by restricting chordin (CHRD) activity on the dorsal side. Acts by facilitating the association between the tolloid proteases and their substrate chordin (CHRD), leading to enhance chordin (CHRD) degradation (By similarity). May have matrix-related function involved in placental and embryonic development, or play a similar role in other physiological processes.
Synonyms: HNOEL-iso; OLF44
Tractability: Antibody: UniProt places it where antibodies can reach, with high confidence; UniProt predicts a signal peptide or a membrane-spanning region; its Gene Ontology location is reachable by antibodies, with medium confidence.
Gene: Protein-coding gene on chromosome 1 (113,979,024 to 114,035,572, forward strand). Ensembl gene ENSG00000116774.
Subcellular location: Secreted
Subcellular location (Human Protein Atlas): Vesicles; Predicted to be secreted
Gene Ontology:
Biological process: signal transduction
Cellular component: extracellular vesicle; extracellular region
Genetic constraint (gnomAD): Loss-of-function variants: 24 observed, 34.33 expected, observed/expected ratio (o/e) 0.7, 90% interval 0.5 to 0.98. The upper end of that interval is the gene's LOEUF score, 0.98, which puts it in group 4 of 6, group 1 being the genes least tolerant of losing a copy. Missense variants: 494 observed, 531.19 expected, observed/expected ratio (o/e) 0.93, 90% interval 0.86 to 1. Synonymous variants: 182 observed, 205.73 expected, observed/expected ratio (o/e) 0.88, 90% interval 0.78 to 1.
Homologues: Orthologues: chimpanzee OLFML3 (100% identical), dog OLFML3 (96% identical), pig OLFML3 (96% identical), rat Olfml3 (95% identical), guinea pig OLFML3 (95% identical), mouse Olfml3 (94% identical), tropical clawed frog olfml3 (55% identical), zebrafish olfml3b (50% identical), zebrafish olfml3a (44% identical). Paralogues in human: OLFML1 (32% identical), MYOC (25% identical), OLFML2A (25% identical), OLFML2B (24% identical), OLFM1 (24% identical), OLFM4 (21% identical), OLFM2 (21% identical), OLFM3 (20% identical), GLDN (17% identical).
Diseases named in the same sentence as OLFML3 in open-access papers:
OLFML3 is named in the same sentence as 35 diseases in open-access papers, as found by Europe PMC text mining. Sharing a sentence is not in itself a finding about the gene and the disease. The quoted sentences say what the papers report.
glioblastoma (11 papers, 2020 to 2026). The most malignant astrocytic tumor (WHO grade IV). "LOX influences macrophage infiltration through NF-κB-PATZ1 signaling, while CLOCK modulates microglial recruitment via the OLFML3 axis, both contributing to immune suppression in glioblastoma." (PMID 40076738, 2025). "There has also been a study that demonstrates the inhibitory effect of CLOCK on glioblastoma through the OLFML3-HIF1α-LGMN pathway." (PMID 38703241, 2024). "For example, BMAL1::CLOCK recruits immune-suppressive microglia cells to the TME of glioblastoma (GBM) via transcriptional activation of the OLFML3 gene." (PMID 36937362, 2023). "Expression of the circadian gene CLOCK specifically demonstrates a positive correlation with LMGN and OLFML3 in glioblastoma." (PMID 38173841, 2023). "OLFML3 was found to function as an immunosuppressive molecule during the carcinogenesis of glioblastoma." (PMID 34686207, 2021). "While low-grade gliomas (LGG, n = 592) had increased OLFML3 mRNA levels relative to normal brain ((Normal, n = 1141; p < 0.001), glioblastomas (GBM, n = 166) had increased OLFML3 mRNA expression relative to both LGG (p < 0.001) and normal brain (p < 0.001)." (PMID 34884869, 2021). "A specific signaling pathway between GSCs and microglia, the CLOCK-olfactomedin-like 3 (OLFML3)-HIF1α-legumain (LMGN)-cluster of differentiation 162 (CD162) axis, has been identified and serves as a potential therapeutic target for glioblastoma." (PMID 38173841, 2023). "Likewise, the upregulation of chemoattractant olfactomedin-like 3 (OLFML3) by BMAL1 and CLOCK facilitates the migration of immunosuppressive microglia into the glioblastoma TME." (PMID 39413708, 2024).
glioma (11 papers, 2019 to 2025). A benign or malignant brain and spinal cord tumor that arises from glial cells (astrocytes, oligodendrocytes, ependymal cells). "linked glioma CLOCK expression to microglia intra-tumoral infiltration through the Olfactomedin-like 3 (OLFML3)/HIF1α/Legumain (LGMN)/P-selectin glycoprotein ligand-1 (PSGL-1) axis." (PMID 40642066, 2025). "(b) The log-fold change expression of SGmic genes (P2ry13, P2ry12, Gpr34, Slc2a5, Siglec-H, Olfml3, Tmem119, Fcrls) in glioma-associated microglia isolated from RCAS tumors compared to microglia isolated from healthy control brains is shown." (PMID 30764877, 2019). "(c) Graph shows the log-fold change expression of SGmic genes (P2ry13, P2ry12, Gpr34, Slc2a5, Siglec-H, Olfml3, Tmem119, Fcrls) in glioma-associated microglia isolated from GL261 tumors as compared to microglia isolated from healthy control brains." (PMID 30764877, 2019). "(a) The log-fold change expression of SGmic genes (P2ry13, P2ry12, Gpr34, Slc2a5, Siglec-H, Olfml3, Tmem119, Fcrls) in glioma-associated microglia isolated from experimental RCAS tumors compared to microglia isolated from healthy control brains is shown." (PMID 30764877, 2019). "Moreover, loss of Olfml3 attenuated TGFβ-induced restraint on microglial immune function and production of cytokines that are critical in promoting glioma cell malignancy." (PMID 34884869, 2021). "Here, we tested the hypotheses that microglial Olfml3 is integral to the pro-tumorigenic glioma-associated microglia phenotype and promotes glioma cell malignancy." (PMID 34884869, 2021). "Mechanistically, the CLOCK-induced upregulation of OLFML3 enhanced LGMN transcription by modulating HIF1α in glioma stem cells." (PMID 38607733, 2024). "The findings of several recent studies have indicated that OLFML3, EVA1B, and FERMT3 are potential prognostic markers for glioma, which are significantly associated with poor prognosis and tumor immune microenvironment." (PMID 38686055, 2024). "For instance, in a glioma stem cell study, the CLOCK/BMAL1 complex within these cells was found to stimulate tumor angiogenesis within the glioma TME by modulating HIF1α through the transcriptional regulation of OLFML3." (PMID 38607733, 2024). "Correlation analysis showed that the expression level of OLFML3 in glioma tissues was negatively correlated with that of miR-637." (PMID 36755314, 2023). "We have demonstrated that microglia-derived OLFML3 promotes pro-tumorigenic microglia function and glioma cell malignancy." (PMID 36498941, 2022). "While many cell types within the murine CNS express Olfml3, including microglia, endothelial cells (ECs) and glioma cells, the role of OLFML3 in the healthy CNS remains incompletely characterized." (PMID 36498941, 2022). "Considering our previous findings that microglia-derived OLFML3 promotes glioma cell malignancy and a pro-tumorigenic microglia phenotype, these results are particularly exciting." (PMID 36498941, 2022). "Examination of The Cancer Genome Atlas (TCGA) transcriptomic datasets revealed that OLFML3 mRNA expression increased with increasing glioma tumor malignancy." (PMID 34884869, 2021). "Silencing of Olfml3 attenuated the pro-tumorigenic microglial secretome, as well as mitigating glioma cell malignancy in vitro." (PMID 34884869, 2021). "To begin to explore putative sources for increased OLFML3 in GBM, we confirmed Olfml3 expression in a mouse microglia cell line (N9), a mouse glioma cell line (GL261), and primary mouse brain endothelial cells." (PMID 34884869, 2021). "To determine the effect of OLFML3 on the glioma cell malignancy, we exposed GL261 mouse glioma cells to recombinant human OLFML3 (rhOLFML3) for 48 h." (PMID 34884869, 2021). "In this study, we began to uncover the role of Olfml3 in microglial function and glioma cell malignancy." (PMID 34884869, 2021). "Olfactomedin-like 3 (Olfml3), a novel, secreted glycoprotein, is known to promote several non-CNS cancers." (PMID 34884869, 2021).
glioma (continued). "Together, our recent finding that microglia-derived OLFML3 promotes malignant features of glioma cells, coupled with the general angiogenic effects of OLFML3, prompt us to speculate that microglia-derived OLFML3 may also promote EC neoangiogenesis in GBM." (PMID 36498941, 2022). "Indeed, OLFML3 mRNA expression is positively correlated with glioma grade, with the highest expression observed in adult GBM." (PMID 36498941, 2022). "Taken together, our data suggest that Olfml3 may serve as a gatekeeper for TGFβ-induced microglial gene expression, thereby promoting the pro-tumorigenic microglia phenotype and glioma cell malignancy." (PMID 34884869, 2021). "While it is a direct TGFβ1 target gene in microglia, the role of microglia-derived OLFML3 in glioma progression is unknown." (PMID 34884869, 2021). "However, it is interesting to consider the interconnectedness of these systems and their possible synergistic promotion of OLFML3 expression in microglia and glioma cells alike." (PMID 34884869, 2021). "Importantly, microglia-derived OLFML3 directly contributes to glioma cell malignancy through increased migration and invasion." (PMID 34884869, 2021). "Our results support the hypothesis that microglia-derived OLFML3 acts as a paracrine factor facilitating glioma cell invasion." (PMID 34884869, 2021). "Herein, our data demonstrated that microglia-derived Olfml3 may contribute to glioma cell malignancy through intrinsic and extrinsic mechanisms." (PMID 34884869, 2021). "Glioma cell migration and invasion were only affected following 48 h exposure to rhOLFML3, suggesting that OLFML3 may regulate key signaling pathways in glioma cells." (PMID 34884869, 2021). "In addition, a literature analyzed the immune-related signature in glioma and suggested that the expression of OLFML3 might additionally mirror an irregular immune condition." (PMID 37808305, 2023). "Importantly, our data suggest that OLFML3 may directly contribute to glioma cell malignancy through increasing migration and invasion capacity." (PMID 34884869, 2021). "Thus, OLFML3 may have cell type-specific functions within the glioma microenvironment that collectively support tumor growth." (PMID 34884869, 2021). "While exploration of the role of OLFML3 in GBM has just begun, depletion of OLFML3 in human glioma cells was found to reduced GAM infiltration and extend survival in a glioma xenograft mouse model." (PMID 36755314, 2023). "Our previous work has demonstrated that microglia-derived OLFML3 is also relevant in GBM, as it promotes a pro-tumorigenic microglial phenotype and glioma cell malignancy." (PMID 36498941, 2022). "While the role of OLFML3 in GBM has just begun to be explored, depletion of OLFML3 in human glioma cells reduced GAM infiltration and extended survival in a glioma xenograft mouse model." (PMID 34884869, 2021). "While exposure to conditioned medium (CM) from isogenic control microglia pre-treated with TGFβ increased mouse glioma cell (GL261) migration and invasion, this effect was abolished with exposure to CM from TGFβ-treated Olfml3-/- microglia." (PMID 34884869, 2021). "Recent studies have shown that olfactomedin Like 3 (OLFML3) exhibits an anti-glioma effect by regulating GAMs infiltration under the influence of the biological clock, and a positive correlation between the survival of GBM patients and the expression level of OLFML3 has been reported." (PMID 36969167, 2023). "Moreover, OLFML3 was highly expressed in glioma patients with relapse compared with glioma patients without relapse." (PMID 36755314, 2023).
colorectal cancer (4 papers, 2021 to 2023). A primary or metastatic malignant neoplasm that affects the colon or rectum. "Targeting OLFML3 in colorectal cancer suppresses tumor growth and angiogenesis and increases the efficacy of anti-PD1-based immunotherapy." (PMID 36755314, 2023). "Antibody-mediated inhibition of OLFML3, as well as genetic silencing of Olfml3, resulted in reduced tumor vascularization and growth, which ultimately prolonged survival in mouse models of lung and colorectal cancer." (PMID 36498941, 2022). "Clinically, high OLFML3 expression correlates with reduced disease-free survival in human colorectal cancer patients, suggesting a potential role as a therapeutic target." (PMID 34572851, 2021). "Here, we examined the expression of OLFML3 mRNA and protein in human tumors, including colorectal cancer (CRC) and lung carcinoma." (PMID 34572851, 2021). "In support of this hypothesis, recent work has demonstrated that anti-OLFML3 therapy in conjunction with anti-PD1 immunotherapy increased overall survival in a mouse model of colorectal cancer." (PMID 34884869, 2021). "Inhibition of OLFML3 suppresses the growth of colorectal cancer in preclinical models." (PMID 34572851, 2021). "We focused on colorectal cancer (CRC), as elevated expression of OLFML3 mRNA correlated with shorter relapse-free survival, higher tumor grade, and angiogenic microsatellite stable consensus molecular subtype 4 (CMS4)." (PMID 34572851, 2021).
viral infection (4 papers, 2021 to 2025). "After this screening, four genes (STAG2, CD40LG, SMARCA2 and OLFML3) were found to have predictively high scores from the databases and their established links to the immune response and viral infection." (PMID 40981223, 2025). "While OLFML3 promoted viral infection by antagonizing type I IFN signaling, it could reduce the severity of LPS- and PAO1-induced ALI in mice by promoting macrophage phagocytosis and migration." (PMID 40083707, 2025). "Our study is the first to define OLFML3 as an IFN signaling inhibitor and to connect the functions of OLFML proteins to viral infections." (PMID 34686207, 2021). "Nevertheless, it is not completely unreasonable to expect the activities of OLFML3 in viral infections given the general roles of other OLFML proteins in inflammation and apoptosis and the signaling molecules these pathways share." (PMID 34686207, 2021). "Some studies have suggested that OLFML3 may be involved in development and tumorigenesis but none has reported its role in viral infection." (PMID 34686207, 2021). "However, the role of OLFML3 is poorly understood and there have been no studies reporting its functions with viral infection." (PMID 34686207, 2021).
lung carcinoma (3 papers, 2021 to 2023). "Tumor vasculature coverage by pericytes, cells which are necessary for EC survival, was reduced following anti-OLFML3 therapy in a lung carcinoma model." (PMID 36498941, 2022). "Lung carcinoma cell migration and invasion were affected following only 48 h of exposure to rhOLFML3, suggesting that OLFML3 may regulate key signaling pathways in lung carcinoma cells." (PMID 36755314, 2023). "Interestingly, targeting Olfml3 by polyclonal antibodies inhibits tumor growth in a mouse model of lung carcinoma." (PMID 34572851, 2021).
breast carcinoma (2 papers, 2021 to 2022). "Because breast cancers are poorly, or at best moderately, responsive to anti-VEGF-A therapy and immune checkpoint blockade, it would be interesting to study the effect of inhibiting OLFML3 in breast cancer models." (PMID 34572851, 2021). "Moreover, transcriptional repression of Olfml3 by the Breast Carcinoma Metastasis Suppressor gene inhibited cell migration and invasion in breast cancer cell lines, indicating its relevance in epithelial-to-mesenchymal transition and metastasis." (PMID 36498941, 2022).
prostate carcinoma (2 papers, 2019 to 2021). A carcinoma that arises from epithelial cells of the prostate gland. "Comparably higher expression of Olfml3 has been detected in the stroma transcriptome of osteoblastic bone metastases of prostate cancer." (PMID 31083655, 2019).
acute lung injury (1 paper, 2025). A condition of lung damage that is characterized by bilateral pulmonary infiltrates (pulmonary edema) rich in neutrophils, and in the absence of clinical heart failure. "We first investigated the in vivo functions of OLFML3 in LPS- or Pseudomonas aeruginosa (PAO1, ATCC-BAA-47; strain HER-1018)-induced acute lung injury (ALI) model in mice using a global Olfml3 knockout mouse line derived from C57BL/6 background." (PMID 40083707, 2025). "In LPS- or Pseudomonas aeruginosa-induced acute lung injury (ALI) mouse model, OLFML3 depletion exacerbated inflammatory response, leading to reduced survival." (PMID 40083707, 2025).
allergic disease (1 paper, 2021). An immune response that occurs following re-exposure to an innocuous antigen, and that requires the presence of existing antibodies against that antigen. "Additionally, several proteins, whose expression could be regulated by these variants, had been previously associated with asthma-related traits and/or allergic diseases (e.g., OLFML3, PCSK3, ZNF180, GALNT16, and KLK14)." (PMID 34442380, 2021).
Alzheimer disease (1 paper, 2026). A progressive, neurodegenerative disease characterized by loss of function and death of nerve cells in several areas of the brain leading to loss of cognitive function such as memory and language. "The OLFML3 gene is a protein-coding gene associated with diseases such as Alzheimer’s disease, frontotemporal dementia, and amyotrophic lateral sclerosis." (PMID 41554047, 2026).
atherosclerosis (1 paper, 2025). A disease characterized by the build-up of fatty material and calcium deposition in the arterial wall resulting in partial or complete occlusion of the arterial lumen. "We also found certain HS disaccharides (D0H0) associated with APP and other proteins increased in CAA (OLFML3, FRZB, ApoE, FGA), as well as with ApoE genotype, but not with atherosclerosis." (PMID 40156913, 2025).
colorectal tumors (1 paper, 2021). "We found that in colorectal tumors, recombinant anti-OLFML3 antibody treatment decreases the abundance of mature macrophages and TAMs while increasing the recruitment of NK-like T cells." (PMID 34572851, 2021).
ischemic stroke (1 paper, 2023). A stroke disorder caused by obstruction of blood flow to the brain, due to thrombotic (local blood clot formation) or embolic (due to a blood clot or other material traveling from another site) event. "To explore the detailed transcriptional changes of the highly heterogenous microglia after ischemic stroke, we reclassified microglia and found seven distinct microglia subclusters, MG0–MG6, which all expressed canonical microglia genes, including P2ry12, Hexb, Sparc, and Olfml3." (PMID 37183260, 2023).
Lewis lung carcinoma (1 paper, 2019). "It binds to BMP4 and in xenograft mice models of Lewis lung carcinoma cells, Olfml3 was expressed in tumor endothelial cells and pericytes." (PMID 31083655, 2019).
malignant glioma (1 paper, 2024). A grade III or grade IV glioma arising from the central nervous system. "A study has also reported multiple roles of OLFML3 gene in malignant glioma grades 2 and 3, indicating its potential as a therapeutic target and prognostic marker." (PMID 39348350, 2024).
oral cancers (1 paper, 2024). "This analysis revealed that in addition to the positive control GAPDH, all oral cancers (except SCC4) upregulated the miR-155 downstream targets OLFML3, TBR1, BACH1, ZNF652, IRF2-BP2, and ZIC3." (PMID 38396844, 2024).
retinal diseases (1 paper, 2016). "OLFML3 may play a possible role in angiogenesis in ocular tissues and it has been proposed that this protein may play a role in anterior segment and retinal diseases." (PMID 27821182, 2016).
sarcoma (1 paper, 2021). A usually aggressive malignant neoplasm of the soft tissue or bone. "We have shown that established Rh30 and RD sarcoma cell lines cultured in the presence of the tested PRMT inhibitors have decreased expression of TNC, NRP1, MYOF, EMP1, OLFML3 and CCND1 and increased expression of the GADD45G gene." (PMID 34360791, 2021).